UBE2L6 (ubiquitin conjugating enzyme E2 L6)
Diseases named in the same sentence as UBE2L6 in open-access papers (continued):
Sharing a sentence is not in itself a finding about the gene and the disease.
cancer (10 papers, 2015 to 2026). A tumor composed of atypical neoplastic, often pleomorphic cells that invade other tissues. "Increased expression of Ube2l6 is linked to degradation/suppression of cancer cells and affected downstream apoptotic factors (i.e. Caspase 3, Caspase 9, Bcl-2, Bax)." (PMID 38650655, 2024). "These included several candidate tumor suppressor genes, such as ABLIM1, CYFIP2, VPS13A, SERPINI1, TET2, HTRA4, UBE2L6, as well as oncogenes/genes implicated as biomarkers in other cancers, such as FAM65B and TCF7L2." (PMID 27385100, 2016). "Aberrant expression of UBE2L6 or other members of the ISGylation system have been reported in various cancers." (PMID 28186990, 2017). "Additional studies are needed to explore this potential of UBE2L6 as a therapeutic target for cancer treatment." (PMID 26506425, 2015). "In this study, we report the first instance of epigenetic silencing of UBE2L6 in human cancer." (PMID 26506425, 2015). "However, one reason for this opposite trend may be that UBE2L6, a ubiquitin-conjugating enzyme, can be a negative regulator in certain contexts, such as inhibiting autophagy in cancer cells." (PMID 41378895, 2026). "UBE2L6 has been confirmed by conjugated ISG15, and ISG15 has also been identified as a potential cancer serological marker." (PMID 34773365, 2021). "Three genes ARID2, LRIF1 and UBE2L6 were not covered by any representative term with only ARID2 being an NCG cancer gene." (PMID 34504716, 2021).
tumor (9 papers, 2015 to 2025). "These core genes—TRAF4, UBE2L3, FBXO45, UBE2L6, FBXL14, SKP2, CHAF1B, and WDR77—have been implicated in tumor progression in previous studies." (PMID 40990020, 2025). "To complement these observations, we also analyzed UBE2L6 expression in five random fields of tumor sections and plotted it against EZH2 expression scores, revealing a negative correlation between UBE2L6 and EZH2 (linear regression R2 = 0.62, p < 0.0001)." (PMID 36906655, 2023). "Interestingly, the same correlation was also found in for UBE2L6 mRNA in Luminal B (P value = 0.0169) and basal tumours (P value = 0.0182) with lymph node metastasis." (PMID 34556814, 2021). "UBE2L6 mRNA was completely silenced in 5 of the 37 primary NPC tumor biopsies." (PMID 26506425, 2015). "In the group of novel hub genes, low expression levels of UBE2L6, KIR2DL4, IFIT2, and CLEC4E were observed in tumor cells, while high expression levels of SRPX2 and EDN3 were found in SKCM." (PMID 34660598, 2021). "Further, we tested UBE2L6 transcription levels in six cell lines (CNE1, CNE2, TW03, HNE1, HONE1 and C666-1), 37 NPC primary tumor biopsies and 12 normal nasopharyngeal epithelium by RT-PCR." (PMID 26506425, 2015). "Following subcutaneous injection into mice, tumor formation was impeded in UBE2L6-overexpressing 28:B4:F3 recipient mice compared to controls, although differences in tumor volume were not statistically significant at 15 weeks." (PMID 36906655, 2023). "Ubiquitin/ISG15-conjugating enzyme E2L6 (UBE2L6) is an E2 ubiquitin/ISG15-binding enzyme that has a decisive function in inhibiting cell proliferation and xenograft tumour advancement by interacting with E3 ubiquitin ligase to target c-Myc for proteasomal disintegration." (PMID 36567857, 2022). "The overall expression levels of UBE2L6 was significantly lower in the 37 NPC tumor biopsies as compared to the 12 non-malignant nasopharyngeal epithelium (NNE) tested (p < 0.05)." (PMID 26506425, 2015). "Interestingly, all tumor bearing mice developed lymph node metastasis irrespective of UBE2L6 status (data not shown)." (PMID 36906655, 2023). "Interestingly, all tumor-bearing mice developed lymph node metastasis regardless of UBE2L6 status." (PMID 36906655, 2023).
UBE2L6 also shares sentences with these, for which no sentence is quoted: diabetes (2 papers); Hepatic steatosis (2); Insulin resistance (2); Atrophy (1); Cachexia (1); colorectal cancer (1); glioblastoma (1); Glucose intolerance (1); Hepatitis (1); Hypercholesterolemia (1); Hyperinsulinemia (1); ischemia (1); kidney damage (1); measles (1); Obesity (1); ovarian carcinoma (1); prostate carcinoma (1); psoriasis (1); renal cell carcinoma (1); stomach adenocarcinoma (1); urothelial bladder carcinoma (1); uveitis (1).